IL18 (interleukin 18)
Diseases named in the same sentence as IL18 in open-access papers (continued):
Sharing a sentence is not in itself a finding about the gene and the disease.
meningitis (6 papers, 2013 to 2025). A disorder characterized by acute inflammation of the meninges of the brain and/or spinal cord. "IL-23, IL-18 and sRAGE levels were significantly elevated in infants with culture proven meningitis as compared with the other groups." (PMID 29394248, 2018). "CSF IL-23, IL-18 and sRAGE levels were significantly elevated in infants with culture proven meningitis." (PMID 29394248, 2018). "Levels of IL-1β and IL-18 were elevated in the CSF of patients with meningitis as compared to controls." (PMID 23902681, 2013). "However, the combination of IL-18 with IL-23 and sRAGE showed excellent discrimination for the diagnosis of meningitis." (PMID 29394248, 2018). "The results of our study indicated that in the meningitis mouse model constructed using S. pneumoniae serotype III, the NLRP3 inflammasome, ASC and caspase‐1, IL‐1β and IL‐18 expression all were increased." (PMID 39887961, 2025). "Of the 13 measured, 11 (GM-CSF, IFNγ, IL-1α, IL-1Β, IL-2, IL-4, IL-6, IL-10, IL-12, IL-18, and TNF-α) exhibited higher concentrations in the saliva of pigs with meningitis and S. suis infection." (PMID 40284818, 2025). "The results from this study demonstrate a storm of inflammatory cytokines, such as IL1-α, IL-1β, IL-6, IL-18, TNF-α, and INF-γ, in the 24-h meningitis group." (PMID 31901235, 2020). "In the hippocampus, we observed increased levels of pro-inflammatory cytokines, such as IL1-α, IL1-β, IL-6, IL-18, TNF-α, and INF-γ (P < 0.05) in the 24-h meningitis group." (PMID 31901235, 2020). "Blocking of IL-1β and IL-18 in this meningitis model, led to a decrease in disease severity and which prompted the suggestion that the NLRP and ASC dependent changes are solely IL-1 and IL-18 related." (PMID 23902681, 2013). "When a panel of cytokines (including GM-CSF, IFNγ, IL-1α, IL-1β, IL-1ra, IL-2, IL-4, IL-6, IL-8, IL-10, IL-12, IL-18, and TNF-α) was measured in saliva from healthy pigs and in pigs with meningitis and S. suis infection, upregulation of several cytokines was observed in the diseased animals." (PMID 40284818, 2025). "Compared with controls with no meningitis at presentation, patients with TBM had significantly higher (P < .05) CSF concentrations of 28 of 32 mediators; only CCL2 and IL-17 levels were similar, and IL-18 and C5a had medians equal to 0 in both groups." (PMID 25107295, 2014).
non-alcoholic steatohepatitis (6 papers, 2014 to 2023). "Tim-3 deficiency in nonalcoholic steatohepatitis mice contributed to enhanced production of ROS, IL-1β, and IL-18." (PMID 37393392, 2023).
pancreatic ductal adenocarcinoma (6 papers, 2022 to 2025). An infiltrating adenocarcinoma that arises from the epithelial cells of the pancreas. "Several studies have shown a link between IL18 and cancer, specifically in pancreatic ductal adenocarcinoma (PDAC), where high levels of IL18 are associated with increased mortality and poor disease outcomes." (PMID 38784040, 2024). "In pancreatic ductal adenocarcinoma, elevated IL-18 expression correlates with unfavourable prognosis, potentially mediated through tumour cell invasiveness potentiation and immune evasion mechanisms." (PMID 40738927, 2025).
pneumococcal meningitis (6 papers, 2012 to 2019). An acute purulent infection of the meninges and subarachnoid space caused by Streptococcus pneumoniae, most prevalent in children and adults over the age of 60. "IL-18 gene-deficient mice showed enhanced defense and reduced inflammation during pneumococcal meningitis suggesting that endogenous IL-18 contributes to a detrimental inflammatory response during pneumococcal meningitis and that elimination of IL-18 may improve the outcome of this disease." (PMID 23997430, 2013). "IL1-β and IL-18 CSF measurements from pneumococcal meningitis patients showed no altered cytokine responses in different genotype groups." (PMID 27432718, 2016). "IL-1β, IL-2, IL-4, IL-10, IL-12p70, IL-17, RANTES, TNF-α, IL-18 and IL-33 were not significantly altered in the plasma of mice with pneumococcal meningitis compared to sham controls." (PMID 22455545, 2012). "IL-2, IL-4, IL-10, IL-12p70, IL-17, IFN-γ, TNF-α, IL-18 and IL-33 were not altered in brain homogenates of mice with pneumococcal meningitis compared to sham controls." (PMID 22455545, 2012).
pterygium (6 papers, 2018 to 2024). A wedge-shaped fibrovascular lesion arising from the bulbar conjunctiva and extending to the cornea. "We also evaluated the association between fleshiness and pterygium extension and compared the levels of cytokines, including IL-6, IL-18 and VEGF, in the tears of primary pterygium patients, recurrent pterygium patients and participants without ocular disease." (PMID 33531557, 2021). "Further results demonstrated that MMC injection can significantly inhibit the activation of the NLRP3/Caspase-1 pathway in pterygium tissues and thus decrease the expression of IL-1β and IL-18." (PMID 31827916, 2019). "Functional IL-18 and IL-1β cause all sorts of changes, such as fibrosis, EMT, apoptosis, and abnormal cell proliferation, all of which are included in mechanisms of pterygium genesis." (PMID 29724886, 2018). "However, differences in tear IL-6 and IL-18 concentrations were insignificant between the HCs and pterygium patients (p = 0.371 and p = 0.727, respectively)." (PMID 33531557, 2021). "Thus, we believe that VEGF is a contributing factor in the pterygium pathogenesis, whereas the roles of IL-6 and IL-18 remain inconclusive." (PMID 33531557, 2021). "The geometric mean of the IL-18 concentrations in the pterygium patients with DE was 17.44 times higher (95% CI 5.50–55.25) than that of the HCs without DE (p < 0.001) and 14.85 times higher (95% CI 7.26–30.37) than that of the pterygium groups without DE (p < 0.001)." (PMID 33531557, 2021). "In addition, the mRNA levels of IL-18 in pterygium tissues from group II were also notably lower than those in tissues from group I." (PMID 31827916, 2019). "The expression of nod-like receptor pyrins-3 (NLRP3), caspase-1, IL-18, and IL-1β was analyzed in 60 human pterygium tissues and 60 human conjunctival epithelium tissues using real-time quantitative polymerase chain reaction (qRT-PCR) and Western blot analysis." (PMID 29724886, 2018). "In our study, IL-6, IL-18, and VEGF concentrations in pterygium patients and HCs with DE were significantly higher at 4.16–8.86, 14.85–25.93, and 3.41–8.98 times higher, respectively, than those of the other groups without DE." (PMID 33531557, 2021). "Tear IL-6, IL-18, and VEGF concentrations of the primary pterygium patients were very similar to those of the recurrent pterygium patients." (PMID 33531557, 2021). "Thirty pterygium samples and thirty normal conjunctiva samples were collected and analyzed for NLRP3, caspase-1, IL-18, and IL-1β mRNA expression using qRT-PCR." (PMID 29724886, 2018). "The mRNA of these factors was highly expressed in pterygium samples with statistical difference (NLRP3: P<0.001; caspase-1: P<0.001; IL-1β: P<0.05; IL-18: P<0.01)." (PMID 29724886, 2018). "For instance, CASP1 could participate in pyroptosis through activated IL1B and IL18, and FASLG could be involved in pterygium fibroblasts, suggesting that they might play a role in pterygium pathogenesis." (PMID 38732006, 2024). "The geometric mean of the tear IL-18 concentrations in the HCs with DE was 25.93 times higher (95% CI 5.62–119.76) than that of those without DE (p < 0.001) and 22.08 times higher (95% CI 8.64–56.43) than that of the pterygium groups without DE (p < 0.001)." (PMID 33531557, 2021). "Tear IL-6, IL-18, and tear VEGF were significantly higher in participants with DE, regardless of pterygium status." (PMID 33531557, 2021).
rosacea (6 papers, 2016 to 2025). A chronic erythematous skin disorder that affects the face. "Moreover, increased mast cells in rosacea may be associated with IL-18." (PMID 36742296, 2023). "Whether the IL-18 plays a role in rosacea through angiogenesis or mediating inflammation needs further study." (PMID 36742296, 2023). "However, IL-18 exhibited a higher expression level in rosacea patients compared to healthy donors." (PMID 27941650, 2016). "obtained epidermal mRNA from lesional samples by scratching the skin surface and found that compared with the control group, the rosacea group showed significantly decreased expression of IL-18 no matter the subtype." (PMID 36742296, 2023).
skin cancer (6 papers, 2015 to 2026). "The IL-18 protein has been shown to be overexpressed expressed in common skin tumors." (PMID 26376814, 2015). "Another research reported that TRPV4 expression in keratinocytes of human non-melanoma skin cancer is significantly reduced, and the TRPV4 level is associated with IL-18 secretion, which indicated that TRPV4 might serve as a biomarker for the early diagnosis of skin cancer." (PMID 35558077, 2022).
systemic inflammatory response syndrome (6 papers, 2022 to 2025). SIRS is a serious condition related to systemic inflammation, organ dysfunction, and organ failure. "Furthermore, serum acetylcholine (ACh) reduces the production of inflammatory cytokines (TNF-α, IL-1β, IL-6, and IL-18) through the alpha 7 nicotinic acetylcholine receptor subunit (α7nAChR) hereby preventing systemic inflammatory response syndrome (SIRS) development." (PMID 40299464, 2025). "In trauma, systemic inflammatory response syndrome (SIRS), or severe burns, insulin reduces pro-inflammatory mediators (TNF-a, IL-6, CRP, IFN-y, IL-18)." (PMID 39838305, 2025).
urticaria (6 papers, 2008 to 2024). A vascular reaction of the skin characterized by erythema and wheal formation due to localized increase of vascular permeability. "It was found that urticaria was associated with higher concentrations of IL-6 and IL-17A and lower values of IL-18, IL-23, RANTES and IP-10." (PMID 36539847, 2022). "ROC curve analysis showed that IL-18 as a parameter associated with the acute phase of urticaria had the lowest sensitivity and specificity among the parameters studied (70 and 75%, respectively; cut-off point 123.9)." (PMID 36539847, 2022). "However further studies are necessary to define a pathogenic role of IL-1β, IL-1RA, and IL-18 in urticaria." (PMID 24490166, 2013). "Further, this pilot study highlighted that different cutAEs can manifest with distinct cytokine profiles, such as IL-18 and IL-1β being elevated in patients presenting with urticaria." (PMID 38539560, 2024). "Previous studies have shown elevated IL-18 levels in children with a single episode of AU compared to patients with recurrent urticaria and healthy volunteers." (PMID 36539847, 2022). "The precise role of IL-18 of mast cells in urticaria should be studied in terms of innate or adaptive immune responses." (PMID 26690141, 2015). "Further studies are needed to define the relationship between the clinical severity of urticaria and IL-18." (PMID 26690141, 2015). "Children with single episode of urticaria had higher levels of IL-1RA and IL-18 than healthy subjects." (PMID 24490166, 2013). "Serum levels of IL-1β, IL-1 receptor antagonist (IL-1RA), and IL-18 were measured in 56 children with urticaria and in 41 healthy subjects." (PMID 24490166, 2013). "Very little is known about the role of interleukin-1β (IL-1β) and interleukin-18 (IL-18) in urticaria." (PMID 24490166, 2013). "Serum level of IL-18 in children with single episode of urticaria was significantly higher than in healthy controls and children with recurrent episodes of urticaria (for both P < 0.0005)." (PMID 24490166, 2013). "However, some cytokine signatures in the current study were tailored to specific clinical manifestations, e.g., patients with urticaria show a significant increase in plasma concentrations of IL-18 and IL-1β compared to other cutAEs." (PMID 38539560, 2024). "IL-18 stimulates mast cells and basophils to produce mediators such as histamine and may thus foster the development of urticaria." (PMID 38539560, 2024). "Moreover, in all infected urticaria children (single episode and recurrence urticaria, n = 26) serum levels of IL-1RA and IL-18 were significantly higher than in healthy controls (P < 0.0004, P < 0.001, resp)." (PMID 24490166, 2013). "However, further studies should be conducted on a large population to define a possible pathogenic role of IL-1β, its antagonist receptor IL-1RA and IL-18 in urticaria." (PMID 24490166, 2013). "However, it is still controversial whether IL-18 levels are related with disease severity in urticaria." (PMID 26690141, 2015). "Two papers reported higher IL-18 levels in adults with CU, while other studies did not confirm such an increase or the relationship between IL-18 levels and positive ASST and urticaria activity." (PMID 36539847, 2022). "The possible role of IL-1β and IL-18 in acute spontaneous urticaria has not been studied in children yet." (PMID 24490166, 2013). "Like serum IL-18BP level may differentiate patients with urticaria from those experiencing anaphylaxis, the differences of IL-18BP in plasma might be related to differences in IL-18 neutralization, although plasma IL-18 levels did not seem to differ between the study groups (ISM and AdvSM)." (PMID 38925457, 2024).
Wegener’s granulomatosis (6 papers, 2010 to 2024). "Patients with Wegener’s granulomatosis have high serum levels of both IL-18 and IL-18BP." (PMID 38727246, 2024).
acne (5 papers, 2022 to 2025). An inflammatory process of the sebaceous glands which is characterized by comedones, nodules, papules and/or pustules on the skin. "The activation of the NLRP3 inflammasome promotes the maturation of caspase-1 and triggers the release of the downstream acne-pathogenic cytokines IL-1β and IL-18, which subsequently activates the secondary inflammatory mediators, including IL-6 and IL-832." (PMID 38062074, 2023). "This enzyme mediates the inflammatory response by producing pro-inflammatory cytokines, such as IL-1β and IL-18, which contribute to the development of acne vulgaris." (PMID 41178942, 2025). "In contrast, a recent study revealed the overproduction of IL-18 was present in cases of autoinflammation without susceptibility to MAS such as pyogenic sterile arthritis, pyoderma gangrenosum, and acne (PAPA) syndrome." (PMID 36211331, 2022). "Furthermore, a recent study reported the overproduction of IL-18 in cases of autoinflammation without susceptibility to MAS such as pyogenic sterile arthritis, pyoderma gangrenosum, and acne (PAPA) syndrome." (PMID 36211331, 2022).
anemia (5 papers, 2016 to 2023). A reduction in the number of red blood cells, the amount of hemoglobin, and/or the volume of packed red blood cells. "Altogether, these findings suggest that IL-18 plays a pathogenic role in anemia during MAS." (PMID 37074208, 2023). "Of interest, as in CpG-induced MAS, circulating GM-CSF levels increased in mice with fulminant MAS, suggesting several cytokines downstream of IL-18 are involved in myeloid proliferation and anemia." (PMID 37074208, 2023). "Both female Cish genotypes exhibited similar elevations of specific cytokines, including those associated with anemia, such as TNF-α and IL-6, with only IL-18 levels higher in Cish+/+ mice following infection." (PMID 38029163, 2023). "But HIV-infected patients with anemia that is resolved with cART had lower levels of IL-8, IL-18, IL-22, MIP-1-β and MCP-1 and higher IL-6 and hepcidin levels than patients with persistent anemia, either at T0 and T1." (PMID 29258550, 2017). "Indeed, coherent in vivo and in vitro results indicate that IL-18 indirectly impairs erythropoiesis while favoring myelopoiesis and thus contributes to anemia associated with MAS and potentially with other IL-18-driven inflammatory diseases." (PMID 37074208, 2023). "Patients of group B in our study, who did not recover from anemia, had indeed higher levels of IL-8 and IL-18." (PMID 29258550, 2017).
aneurysm (5 papers, 2013 to 2024). Bulging or ballooning in an area of an artery secondary to arterial wall weakening. "Notably, among the differentially expressed mRNAs predicted to be targeted by the differential miRNAs, were some genes previously experimentally identified to be involved in aneurysm formation or loss of vessel cells, such as TGFBR1, MMPs and IL18 etc.." (PMID 24079748, 2013). "Therefore, downstream activation of critical pro-inflammation factors like IL1B and IL18 in pyroptosis process, might also play a role in aneurysm progression." (PMID 34895131, 2021). "Three hub genes, NLRP3, IL1B and IL18, were identified using Cytoscape software and the WGCNA correlation module, and external validation revealed statistically significant differences between the expression of these hub genes in the ruptured and unruptured aneurysm groups (p < 0.05)." (PMID 37752552, 2023).
atrial fibrillation (5 papers, 2019 to 2025). A disorder characterized by an electrocardiographic finding of a supraventricular arrhythmia characterized by the replacement of consistent P waves by rapid oscillations or fibrillatory waves that vary in size, shape and timing and are accompanied by an irregular ventricular response. "A recent genetic study showed that genetic variation of interleukin-18 is related to a lower risk of atrial fibrillation among people in the Northeast China." (PMID 34671599, 2021). "Finally, we found that DEG between paroxysmal and persistent atrial fibrillation was most significantly associated with the interleukin-18, coagulation, and complement cascade." (PMID 34671599, 2021). "IL-18 expression has also been reported to be increased approximately 2-fold in human atrial fibrillation patients compared with control subjects and closely related to the incidence of atrial fibrillation." (PMID 31427887, 2019). "In addition, circulating IL-18 levels are elevated in patients with atrial fibrillation and may be superior to other inflammatory markers that are known to have elevated levels." (PMID 31427887, 2019).
B-cell lymphoma (5 papers, 2022 to 2024). "The study showed that IL-18 (rs1946518) and NF-κB-94 ins/del (rs28362491) gene polymorphisms contributed to a significantly increased risk for B-cell NHL (p < 0.0001 and p = 0.0029, respectively)." (PMID 38397043, 2024). "IL-15, while not able to protect NK cells alone, enhanced the recovery and function of cryopreserved NK cells when used in combination with IL-18, achieving equipotency in a cytotoxicity assay, and in vivo in a model of disseminated B-cell lymphoma." (PMID 38729924, 2024). "Furthermore, inducing NK cells with a memory-like phenotype by briefly activating them with a cytokine cocktail of IL-12, IL-15 and IL-18 can lead to cytokine-induced memory-like NK cells, which show enhanced responses against NK-resistant B-cell lymphoma." (PMID 35453554, 2022). "We should note, though, that there are also reports in the literature that do not support a prognostic role of IL-18 in B-cell lymphoma patients." (PMID 38397043, 2024).